IL4 (interleukin 4)
Diseases named in the same sentence as IL4 in open-access papers (continued):
Sharing a sentence is not in itself a finding about the gene and the disease.
pulmonary TB (22 papers, 2006 to 2024). "Humoral immunity is also stimulated at the site of disease: pulmonary TB is associated with an increase in the Th2 cytokines IL-4, CCL-4 and SOCS3 in bronchoalveolar lavage (BAL) fluid taken from patients with active pulmonary TB." (PMID 27865379, 2016). "Clinical studies on blocking of IL-4 in patients with pulmonary tuberculosis by pascolizumab (NCT01638520) are ongoing." (PMID 37443495, 2023). "Some studies have reported a relationship between the serum IL-4 levels of pulmonary TB and extrapulmonary TB and healthy controls." (PMID 37327256, 2023). "Recent studies have confirmed that high IL-4 levels are prevalent in patients with TB, particularly those with active pulmonary TB." (PMID 37327256, 2023). "Serum IL-4 levels were significantly different in specific subgroups of studies (Asian, pulmonary TB, cross-sectional studies, and active TB)." (PMID 37327256, 2023). "Although the main finding of elevated blood levels of IL-4 in individuals with active pulmonary TB compared to healthy controls is reliable, a major portion of this heterogeneity remains to be elucidated." (PMID 37327256, 2023). "IL-10 together with IP-10 and IL-4 differentiated pulmonary tuberculosis from latent cases with a sensitivity and specificity of 77.1% and 88.1%, respectively." (PMID 32962082, 2020). "A clinical trial investigating the adjunctive potential of IL-4 blockade (anti-human IL-4 monoclonal antibody, pascolizumab) in patients with DS pulmonary TB undergoing anti-TB treatment is currently underway (NCT01638520)." (PMID 27301245, 2016). "In untreated mice, our model of pulmonary tuberculosis at the chronic infection stage (d60) is characterized by elevated lung CFUs and by increased production of IL-4 while IFN-γ production remains elevated." (PMID 25915045, 2015). "Both of these peripheral blood studies are consistent with our finding of very low levels of serum IL-4 in the majority of patients with pulmonary tuberculosis." (PMID 22815689, 2012). "The aim of our study was to investigate whether IL6–174 G>C SNP and IL17A -197 G>A polymorphism and additional cytokine genes involved in immune response to MTB (IL2, IL4, IL10, IFNG and TNF) are associated with genetic susceptibility to pulmonary TB (PTB)." (PMID 26840977, 2016). "To validate our results in human TB patients, we here determined the association of distinct variants of the IL4, IL13, IL4RA, IL13RA1, and IL13RA2 genes with cavity formation in a large Ghanaian cohort of HIV-negative individuals with newly diagnosed pulmonary TB." (PMID 26977119, 2016). "Moreover, IL-4 producing T-cells have been found in the circulation of patients with pulmonary TB at diagnosis that disappeared rapidly following initiation of chemotherapy." (PMID 25803478, 2015). "However, the immune role of IL-4 in pulmonary TB remains controversial." (PMID 38650928, 2024). "As highlighted previously, our findings indicate that monitoring acute phase parameters (ESR, CRP), Th1 cytokines (IL-2) and anti-inflammatory (IL-4) may help understanding the multidimensionality of immunopathology in TB and point to novel potential therapeutic targets for pulmonary TB." (PMID 27494953, 2016). "Thus, active pulmonary TB is characterized by a decreased antigen-specific IL-4 response." (PMID 23544075, 2013). "The expression of significant cytokines in the immune response during pulmonary TB (IFN-γ, IL-4, TNF- α, and TGF-β) was determined." (PMID 37284503, 2023). "The levels of IFN-γ (OR = 4.06) and IL-4 (OR = 2.62) were more likely to be elevated in the TB group (p = 0.05), and IFN-γ levels were lower in patients with extrapulmonary TB compared to those with pulmonary TB (OR = 0.11; p = 0.0050)." (PMID 36296351, 2022).
rhinitis (22 papers, 2010 to 2024). An inflammation of the mucous membrane lining the nose, usually associated with nasal discharge. "In a murine model of rhinitis, oral administration of B.breve reduced the symptoms and serum specific-IgE, IL-4, IL-10, andincreased CD4+CD25+ T-regulators." (PMID 38687061, 2024). "Treatment of HNECs with IL-4 and IL-13, which are highly concentrated in the nasal epithelium of rhinitis patients, decreases the expression of ZO-1 and Occludin, components of tight junctions." (PMID 39108557, 2024). "Allergic rhinitis, eosinophilic rhinosinusitis, Rhinitis, asthma, and atopic dermatitis are allergic diseases controlled type 2 inflammatory cytokine such as IL-4 and IL-13." (PMID 39108557, 2024). "It is noteworthy that nanobody H5, applied to the apical air side of HNECs of rhinitis patients, shows statistically superior performance in blocking the dual signaling of IL-4/IL-13 compared to dupilumab." (PMID 39108557, 2024). "Xin-Yi-Qing-Fei-Tang has been commonly used for rhinitis and has been shown to reduce eosinophil, serum IgE and IL-4 levels." (PMID 30497462, 2018). "Nasal biopsies of rhinitis patients showed increased IL-4, IL-5, IL-13 mRNA expression suggesting a Th2 cytokine profile." (PMID 24116013, 2013). "Therefore, we used HNEpCs to investigate the mechanisms underlying the anti-rhinitis activity of CSLW and found that CSLW significantly inhibited the accumulation of eosinophils and upregulation of periostin, MUC5AC, and ROS in IL-4- and IL-13-stimulated HNEpCs in a concentration-dependent manner." (PMID 36421442, 2022).
systemic sclerosis (21 papers, 2005 to 2025). A chronic disorder, possibly autoimmune, marked by excessive production of collagen which results in hardening and thickening of body tissues. "In systemic sclerosis, mycophenolic acid induces monocyte/macrophage apoptosis, blunts IL-4–driven activation, and diminishes dermal myeloid signatures, inhibiting fibroblast activation." (PMID 40650314, 2025). "In CTD-ILD, the autoimmune milieu often contains abundant Th2 cytokines; for example, patients with systemic sclerosis-ILD have elevated serum levels of IL-4 and IL-13, which favor M2 polarization." (PMID 41465549, 2025). "High levels of IL-4 were reported in patients with systemic sclerosis, where it plays a pathogenetic role, inducing the formation of the extracellular matrix." (PMID 37630981, 2023). "Systemic sclerosis (SSc) patients have an increased frequency of CD21low B cells and of serum interleukin-4 (IL-4) and IL-21, each possible markers of joint involvement in inflammatory arthritis." (PMID 37763102, 2023). "Tregs from skin affected by systemic sclerosis produced significant amounts of profibrotic cytokines IL-4 and IL-13, which are characteristic of Th2 cells." (PMID 36428461, 2022). "In line with our results, IL-4 has been involved in the persistent downregulation of DPT expression in skin fibroblasts in patients with systemic sclerosis, a fibrotic disorder." (PMID 36012487, 2022). "It was reported that miR151-5p can effectively ameliorate osteopenia in systemic sclerosis (SSc) by targeting IL-4." (PMID 32478058, 2020). "Nevertheless, specific cytokines which were detected in such low levels in AAV were significantly elevated in systemic sclerosis: IL-4, IL-6, IL-17A, and IL-22." (PMID 31286195, 2019). "Indeed, the targeting of IL-4 and IL-13 has been tested in various fibrotic diseases, including systemic sclerosis." (PMID 37630981, 2023). "PF4 functions in integrin-dependent mechanism controlling angiogenesis, promotes the expression of pro-fibrotic cytokines such as IL-4 and IL-13, enhances the proliferation of regulatory T cells, and plays a role in multiple diseases including systemic sclerosis and antiphospholipid syndrome." (PMID 36091001, 2022). "In a mouse model of systemic sclerosis, the IL-4-producing cell proportion was significantly higher in wild-type Tregs co-cultured with Fli1+/- fibroblasts (which overproduced IL-33) than in those co-cultured with wild-type fibroblasts, which were canceled by neutralizing anti-IL-33 antibody." (PMID 36428461, 2022). "Compared with CD4 single-positive T cells, the DPT cells can produce more IL-4 and may be involved in the pathogenesis of systemic sclerosis." (PMID 34095321, 2021). "A number of diseases of abnormal host immunity such as chronic graft vs host disease and systemic sclerosis are characterised by Th2 cells secreting IL-4 which subsequently plays a role in the activation and recruitment of B cells producing IgE, mast cells and eospinophils." (PMID 22815689, 2012). "In CTD-ILD, particularly systemic sclerosis-ILD, a distinct Th2 skew is evident, with higher IL-4 levels in bronchoalveolar lavage fluid in systemic sclerosis-ILD than in that from nonfibrotic controls." (PMID 41465549, 2025). "In systemic sclerosis, the DPT cells in the patient's skin tissue can produce high levels of IL-4 to exert immunosuppressive functions." (PMID 34095321, 2021). "While Romilkimab, which blocks IL-4 and IL-13, has been shown to effectively reduce dermal thickening in systemic sclerosis, it has not been shown to significantly improve lung function, underscoring the challenge of reversing fibrosis once established." (PMID 41465549, 2025). "The TGF-β signaling pathway significantly influences inflammation by modulating Th cell differentiation and reducing JMJD3-mediated production of cytokines such as IL-2, IL-4, and IFN-γ, as evidenced in systemic sclerosis (SSc)." (PMID 39315124, 2024).
systemic sclerosis (continued). "When searching for “systemic sclerosis” and cytokines in the PubMed database, TGF-β had the highest number of hits, followed by IL-6, IL-4, tumor necrosis factor (TNF)-α, platelet-derived growth factor, IL-10, IL-13, IL-1, IL-2, and IL-17 indicating cytokines are related to the pathogenesis of SSc." (PMID 34064515, 2021).
ischemia (20 papers, 2012 to 2025). A hypoperfusion of the BLOOD through an organ or tissue caused by a PATHOLOGIC CONSTRICTION or obstruction of its BLOOD VESSELS, or an absence of BLOOD CIRCULATION. "Exosomes derived from MSCs can ameliorate inflammation after acute ischemia or ischemia–reperfusion injury by modulating anti-inflammatory molecules (IL-4 and IL-10) and pro-inflammatory cytokines (IL-6, TNF-α, and IL-1β), and inhibiting microglia activation." (PMID 40771978, 2025). "The inhibition of PPARγ expression by translocator protein ligands inhibits IL‐4‐induced M2 polarization at the site of hypoxic ischemia in the brain." (PMID 39737788, 2025). "Altogether, our results confirmed that not only IL-4 but also LPS promoted angiogenesis in the mouse hindlimb ischemia model." (PMID 39707436, 2024). "Previous studies detected rapid production of neuronal IL-4 during sub-lethal ischemia and upregulation of TGF-β1 and Arg1 in ischemic brain vessels." (PMID 33757565, 2021). "It was demonstrated that the sustained or increased expression of endogenous anti-inflammatory cytokines (IL-4 and IL-13) contributed to neuronal survival from ischemia-reperfusion injury in the gerbil hippocampus after transient forebrain ischemia." (PMID 34679060, 2021). "Recent evidence shows that neurons that survive a noxious stimulus (i.e., ischemia) respond by increasing the production and release of IL-4." (PMID 30995916, 2019). "Among the modulatory molecules that could be involved in the post-ischemia outcome of HFD mice are IL4 and IL10." (PMID 39624169, 2024). "One limitation of our study is the inability to determine whether 2′-FL promotes IL-4 production directly or indirectly in the brain after ischemia." (PMID 37372011, 2023). "Polarization of microglia induced by IL-4 increased miR-26a in microglia-generated exosomes, which may promote tube formation in vitro and angiogenesis in vivo after ischemia." (PMID 32962207, 2020). "The interleukin-4 (IL-4) observed in the brain after ischemia performs regulatory functions." (PMID 31514749, 2019). "The upregulation of let-7a-5p in microglia has been found to correlate with protection from ischemia and neuroinflammation by inhibiting the expression of pro-inflammatory factors (e.g., IL-6, iNOS) and boosting the expression of anti-inflammatory factors (IL-10 and IL-4)." (PMID 35682695, 2022). "Two-way ANOVA demonstrated no significant main effect of solution or ischemia duration, nor interaction effect, on IL-4 concentration (F (8.48) = 0.81, p = 0.599, partial η2 = 0.13)." (PMID 40729334, 2025). "Collectively, these findings indicate that, within the studied range, neither the choice of cardioplegic solution nor the duration of ischemia had a statistically significant impact on the myocardial release of IL-4, IL-6, IL-10, leptin, TNF-α following ischemia/reperfusion injury." (PMID 40729334, 2025). "The addition of inflammatory medium OGD + LPS or OGD + IL-4 both resulted in significantly lower calcein RFU compared with the untreated normoxia control; however, the media with addition of ND2158 reversed the RFU, suggesting the inhibition of IRAK4 can increase neuronal survival in ischemia." (PMID 33573200, 2021). "As a consequence, IFN‐γ/IL‐4 ratio (index of Th1/Th2 cell balance) resulted significantly higher in ischemic quadriceps (7.3‐fold), and gastrocnemius (3.8‐fold) muscles during early phase of ischemia (P < 0.05 vs. respective nonischemic muscles)." (PMID 24744903, 2014).
metabolic syndrome (20 papers, 2018 to 2024). A cluster of metabolic risk factors for CARDIOVASCULAR DISEASES and TYPE 2 DIABETES MELLITUS. "The results found that HDPs reduced medium-dose alcohol-caused dyslipidemia (significantly elevated T-CHO, TG, LDL-C), elevated liver glycogen levels, and inhibited intestinal-hepatic inflammation (significantly decreased IL-4, IFN-γ and TNF-α), consequently reversing hepatic pathological changes." (PMID 38672817, 2024). "By contrast, whereas the circulating levels of IFNγ, a cytokine that is released by Th1 lymphocytes, were not different between patients and controls, the anti-inflammatory cytokine IL-4, which Th2 lymphocytes mainly produce, was significantly lower in the circulation of metabolic syndrome patients." (PMID 31109070, 2019). "Those with metabolic syndrome were significantly older (p = 0.000), and levels of MDA (p = 0.003), homocysteine (p = 0.001), IL-6 (p = 0.017) and IL-4 (p = 0.000) were significantly higher among them." (PMID 37571341, 2023). "In contrast, a clinical study in 25 subjects with metabolic syndrome showed intravenous vit C administration increased the expression of inflammatory-related genes such as TNF-α, Interleukin 4 (IL-4), and Interferon-gamma (IFN-γ) in the mononuclear cells." (PMID 35949307, 2022). "For example, lower levels of anti-inflammatory cytokines, including IL-4, IL-13, and IL-10, have been found in obese subjects with metabolic syndrome compared to those without metabolic syndrome." (PMID 36313072, 2022). "The increasing trend of IL-6 and Il-1β can be explained by antipsychotics (especially atypical antipsychotics) side effects such as metabolic syndrome in the long period, as increased levels of IL-6, IL-1β, TNF-α, IL-2, IFN-γ, and IL-4 have been reported in patients with metabolic syndrome." (PMID 31908647, 2019). "Indeed, some CD8+ cell-derived cytokines, such as TNFα, are significantly elevated in a metabolic syndrome scenario, whereas those that are derived from CD4+ lymphocytes either remained unchanged or decreased (IL-4)." (PMID 31109070, 2019).
osteoporosis (20 papers, 2012 to 2024). A condition of reduced bone mass, with decreased cortical thickness and a decrease in the number and size of the trabeculae of cancellous bone (but normal chemical composition), resulting in increased fracture incidence. "The overexpression of IL-4 reduced bone formation by osteoblasts and caused osteoporosis of both cortical and trabecular bones; although, IL-4 inhibited the receptor activator of nuclear factor kappa-Β ligand (RANKL)-induced osteoclastogenesis mediated by c-Fos and NFATc1 expression in osteoclasts." (PMID 36362231, 2022). "On the other hand, lymphocyte-specific IL-4 transgenic mice (lck-IL-4 transgenic mice) exhibited osteoporosis by decreasing osteoblast-induced bone formation." (PMID 35163028, 2022). "Our present results that IL‐4 production by NKT‐like cells was suppressed in mice with alcohol‐induced osteoporosis support these findings." (PMID 34214248, 2021). "In the present study, IL‐4 production by NKT‐like cells was significantly decreased in mice with alcohol‐induced osteoporosis." (PMID 34214248, 2021). "In clinical settings, several studies have demonstrated that postmenopausal women with osteoporosis have significantly lower levels of serum IL-4 compared to controls." (PMID 33007863, 2020). "IL-4 inhibits bone resorption both in vivo and in vitro, thus clearly suggesting an osteoprotective role of the Th2 lymphocyte profile in osteoporosis." (PMID 32069819, 2020). "In contrast, cytokines of the Th2 profile, such as IL-4, and regulatory cytokines, such as IL-10, have a predominantly osteoanabolic function and are usually considered protective against osteoporosis." (PMID 32069819, 2020). "On the contrary, regulatory cytokines, such as IL-10, and Th2 cytokines, such as IL-4, exert a prevalent bone anabolic action so as to be regarded as protective against osteoporosis." (PMID 30846811, 2019). "It has been proposed that osteoporosis represents a Th1 and Th17 mediated bone inflammation, whereas Th2 cytokines, such as IL-4, display an antiosteoporotic protective function." (PMID 26449657, 2015). "Conversely, the levels of IL-4 and IL-10 were lower in RA patients with osteoporosis." (PMID 37238933, 2023). "The authors also suggested that a combination of DAS28 (a disease activity score), IL-4, IL-10, and IL-17 could predict the incidence of osteoporosis in RA." (PMID 35955873, 2022). "Furthermore, OCH can prevent alcohol‐induced osteoporosis by stimulating IL‐4 and IFN‐γ production by both NKT‐like and iNKT cells." (PMID 34214248, 2021). "However, levels of IL-4 and osteocalcin were significantly lower in women with osteoporosis (P = 0.007) and (P = 0.028), respectively." (PMID 28121926, 2017). "The differences in OPG, RANKL, IL-4 and IL-10 levels we observed between CD and UC patients confirm a different pathophysiology of these two diseases and a different molecular background of coexisting osteoporosis." (PMID 27639566, 2016). "However, through both its direct and indirect functions, increasing serum levels of IL-4 may be an effective treatment strategy to target osteoporosis." (PMID 33007863, 2020). "In postmenopausal osteoporosis patients, serum IL-17A is significantly higher, while the IFN-γ and IL-4 are significantly lower, suggesting osteoporosis may be more associated with the Th17 cells rather than the Th1 or Th2 cells." (PMID 33408628, 2020). "Research also showed that resistin, leptin, IL-1, IL-4, IL-6, and TGF-β played a significant role in postmenopausal women’s bone metabolism and could be used as a diagnostic marker capable of recognizing patients at risk of osteoporosis and thereby predicting the risk of fracture." (PMID 33519717, 2020). "Similarly, various other biomaterial coatings, e.g., Bioglass, silk sericin, LPS, Chitosan, IL-4, Zinc, GPTMS, wound-healing peptides, aspirin and anti-osteoporosis drugs, showed functionalization of the surface while maintaining the underlying topography." (PMID 36295379, 2022).